CDK4 (cyclin dependent kinase 4)
Diseases named in the same sentence as CDK4 in open-access papers (continued):
Sharing a sentence is not in itself a finding about the gene and the disease.
breast cancer (continued). "Notably, Mps1 inhibition has shown potential in overcoming resistance to CDK4/6i in ER + breast cancer." (PMID 40949156, 2025). "This study suggests that PRMT5 inhibition could be a potential therapy in overcoming CDK4/6i resistance in advanced ER + breast cancer." (PMID 40650785, 2025). "Abemaciclib, palbociclib, and ribociclib are three oral CDK4/6 inhibitors that successfully secured FDA approval for advanced breast cancer (BC) patients with hormone receptor-positive (HR +) and human epidermal growth factor receptor 2-negative (HER2-) tumor status." (PMID 40856900, 2025). "Overall, we demonstrate how ErbB2 receptor levels modulate the roles of cyclin D1 and c-Myc in the G1/S transition and suggest that variations in ErbB2 levels within breast cancer tissues confer heterogeneous sensitivity to CDK4 inhibitors, potentially complicating treatment." (PMID 41161384, 2025). "For this reason, CDK4/6 inhibitors are being used more frequently to treat HR+/HER2− breast cancer." (PMID 40149372, 2025). "Due to the importance of the CDK4/6-USP51 signaling pathway in the treatment of advanced breast cancer, we selected this signaling pathway for this study to investigate whether ribociclib affects the mRNA expression of genes involved in this pathway." (PMID 39196911, 2024). "However, (a) expression of aeTSAs (e.g., from the MAGE family) can be enhanced by hypomethylating agents, and (b) one family of hypomethylating drugs (CDK4/6 inhibitors) is currently used as the first line of treatment in HR+ breast cancer." (PMID 37906288, 2024). "Thus, PRMT5 represents an actionable therapeutic vulnerability in breast cancers of this genotype and potentially fulfills an unmet need for patients with acquired resistance to CDK4/6i." (PMID 38480701, 2024). "All patients with HR+/HER2− ABC who received endocrine therapy +—a cyclin-dependent kinase 4/6 inhibitor as first-given systemic therapy in 2007–2020 in the Netherlands were identified from the Southeast Netherlands Advanced Breast Cancer (SONABRE) registry (NCT03577197)." (PMID 37878148, 2024). "A key issue relevant to the clinical development of CDK2 inhibitors in luminal breast cancer is whether they might not only overcome acquired resistance to CDK4/6 inhibition, but also prevent it." (PMID 38047585, 2024). "However, our analysis of patients with breast cancer initiating CDK4/6i therapy between 2018 and 2021 demonstrated that the COVID-19 pandemic did not impact treatment adherence." (PMID 39766060, 2024). "While it facilitated resistance to CDK4/6 inhibitors in breast cancer." (PMID 38962317, 2024). "Moreover, CDK4/6 inhibitors can delay tumor recurrence in a transgenic HER2‐positive breast cancer model." (PMID 38469548, 2024). "Our findings suggest that while both CDK4/6 inhibitors effectively modulate key biological pathways in HR+/HER2- breast cancer, nuances in their impact, particularly on the HER2-enriched signature, are dose-dependent, influenced by the addition of fulvestrant and warrant further investigation." (PMID 38992220, 2024). "Moreover, CDK4/6i are typically administered in conjunction with anti‐hormonal therapy, such as AI, in clinical practice for breast cancer treatment." (PMID 37854019, 2024). "This emerging finding highlights the potential importance of early detection of gBRCAm in patients with hormone receptor-positive breast cancer ahead of treatment selection, especially in light of recent CDK4/6 inhibitor approval in the early breast cancer setting." (PMID 39237557, 2024). "Nevertheless, it remains uncertain whether HER2 signaling affects the effectiveness of CDK4/6 inhibitor administered in combination with endocrine therapy for HR+/HER2-low breast cancer and suitable intervention measures." (PMID 39730704, 2024).
breast cancer (continued). "Finally, we examined the combined effect of reparixin with tamoxifen, fulvestrant, and two CDK4/6 inhibitors such as palbociclib and ribociclib which are currently being used in treatment of endocrine resistant breast cancer therapy." (PMID 38393465, 2024). "As new treatment strategies for ER+/Her2− breast cancer, such as CDK4/6 inhibitors, emerge, compliance with adjuvant therapy may change, and indications for SNB may need to be reassessed." (PMID 38383660, 2024). "Predictive biomarkers are urgently needed, not just to define new tumour types that may be sensitive to CDK4/6 inhibitors, but to identify the subset of breast cancer patients most likely to respond well to these drugs." (PMID 38438376, 2024). "Collectively, these preclinical studies suggest that dual pathway targeting by vepdegestrant and CDK4/6 or PI3K/mTOR signaling could result in better therapeutic outcomes for patients with advanced ER+/HER2− breast cancer." (PMID 39767607, 2024). "In our extended experiment, we found that high level of COL11A1 contributed to reduced sensitivity of CDK4/6 inhibitors in ER+ breast cancer cells, suggesting inhibition of COL11A1 may enhance the efficacy of palbociclib, abemaciclib and ribociclib." (PMID 38806505, 2024). "Therefore, we examined the effects of representative DNA‐damaging agents (Cisplatin, Doxorubicin, Etoposide, and Carboplatin) and a CDK4/6i (Palbociclib, Abemaciclib) on the senescence of CDK4/6i‐sensitive breast cancer cells." (PMID 37854019, 2024). "Since deleting UBR5 sensitizes cells to treatment by Cdk4/6 inhibitors, it is possible that current Cdk4/6 inhibitor–based treatments for breast cancer can be improved by developing novel therapeutics targeting Rb degradation through UBR5, which is frequently amplified in these cancers." (PMID 39441926, 2024). "Cyclin-dependent kinase 4/6 inhibitors (CDK4/6is), such as palbociclib, ribociclib, and abemaciclib, have been approved for treating patients with hormone receptor-positive and human epidermal growth factor receptor 2-negative breast cancer." (PMID 38633610, 2024). "Since deleting UBR5 sensitizes cells to treatment by Cdk4/6 inhibitors that are currently used to target breast cancers, we next explored whether UBR5 itself could be a potential therapeutic target." (PMID 39441926, 2024). "In addition, expression of other pro‐angiogenic factors was significantly lower in senescent breast cancer cells induced by CDK4/6i, whereas DNA‐damaging agent‐induced senescence increased expression of pro‐tumorigenic factors, including VEGF." (PMID 37854019, 2024). "Furthermore, these studies suggest that the combination of reparixin and CDK4/6 inhibitors acts as the potential therapeutic regimen to circumvent endocrine resistant breast cancer growth and metastasis." (PMID 38393465, 2024). "Notably, HER2 knockdown increased the inhibitory effect of CDK4/6 inhibitor combined with endocrine therapy on the proliferation of HR+/HER2-low breast cancer cells, as demonstrated by CCK-8 and colony formation assays (P < 0.05)." (PMID 39730704, 2024). "CDK4/6 inhibitors are nowadays the mainstay for HR+/HER2- advanced breast cancer." (PMID 39114308, 2024). "In the realm of HR + /HER2- breast cancer treatment, one of the most significant advancements in recent decades is the emergence of CDK4/6i, which have proven superior to ET alone when combined with it in the majority of patients, underscoring their pivotal role." (PMID 38409585, 2024). "Similarly, the pionERA breast cancer trial (NCT06065748) compares giredestrant plus a CDK4/6 inhibitor of physicians’ choice with fulvestrant plus a CDK4/6 inhibitor of physicians’ choice in the first-line treatment of ER+ HER2− metastatic breast cancer." (PMID 38339371, 2024).
breast cancer (continued). "To characterize and compare senescence induced by treatment with DNA‐damaging agents (Cisplatin and Doxorubicin) and CDK4/6i, we screened various breast cancer cell lines to find out which could achieve stable senescent status for analysis post‐drug treatment." (PMID 37854019, 2024). "In addition to finding PRR11-related mechanisms, the original study reported a cluster of E2F4-regulated genes that were sensitive to subsequent CDK4/6 inhibitor (palbociclib) treatment in a separate cohort of ER+ breast cancer patients." (PMID 39057065, 2024). "Furthermore, the addition of CFI-402257 to breast cancer cell lines resistant to the inhibition of CDK4/6 demonstrated improved anticancer effects." (PMID 39339232, 2024). "We observed similar results in a PDX model (ST4316B) of CDK4/6i–resistant breast cancer." (PMID 38047585, 2024). "Taken together, our study implicates CXCL1 as a critical role in ERBC growth and metastasis via crosstalk with fibroblast and cotargeting CXCR1/2 and CDK4/6 could potentially overcome endocrine resistant breast cancer." (PMID 38393465, 2024). "However, previous studies have indicated controversies regarding the efficacy of CDK4/6 inhibitors in combination with endocrine therapy for HR-positive/HER2-negative early breast cancer." (PMID 39329126, 2024). "Cyclin-dependent kinase 4/6 (CDK4/6) inhibitors have demonstrated a survival benefit in the second-line treatment of patients with hormone receptor-positive human epidermal growth factor receptor 2-negative advanced breast cancer." (PMID 39697231, 2024). "Additionally, TPX2, targeted by the CDK4/6 inhibitor Ademaciclib, has shown advancements in regulating cell cycle progression primarily in HR-positive breast cancer." (PMID 39596419, 2024). "Importantly, this intervention synergistically amplified the efficacy of CDK4/6 inhibitor combined with endocrine therapy in HR+/HER2-low breast cancer by suppressing the HER2 pathway." (PMID 39730704, 2024). "For example, mouse models of breast cancer and other solid tumors have shown that exposure to CDK4/6 blockade can promote T cell-mediated antitumor activity such that this may be further amplified via immune checkpoint inhibition." (PMID 38610930, 2024). "When solely assessing the ER-positive patient group, the median PFS and median OS from our study compared significantly unfavourably, especially in studies evaluating CDK4/6-inhibitors and/or endocrine therapy as first-line treatment for ER-positive advanced breast cancer." (PMID 38912829, 2024). "Limited data exist regarding the role of CDK4/6 and cyclin D1 interaction in the development of palbociclib resistance, and effective targets for palbociclib-resistant ER+ and ER− breast cancers are largely unknown." (PMID 38473336, 2024). "Together, these findings identify a clinically tractable combination strategy for overcoming resistance to endocrine therapy and CDK4/6 inhibitors in breast cancer and provide insight into the potential mechanism of drug efficacy in targeting treatment-resistant disease." (PMID 37801608, 2024). "NATALEE and MonarchE trails found survival benefits of CDK4/6 inhibitors combined with endocrine therapy in HR-positive early breast cancer, whereas the results of the other two studies indicated that CDK4/6 inhibitors did not improve survival outcomes in these patients." (PMID 39329126, 2024). "Furthermore, multiple trials have showcased the efficacy and safety of CDK4/6i in treating breast cancer." (PMID 38166784, 2024). "The combination of CDK4/6 inhibitors (CDK4/6i) with endocrine therapy (ET) has emerged as the foremost therapeutic modality for patients afflicted with hormone receptor-positive (HR + )/HER2-negative (HER2-) advanced breast cancer." (PMID 38409585, 2024). "Thus, CDK4/6 inhibitors (CDK4/6i) found the way into the clinic, in particular for treating breast cancer patients." (PMID 39088265, 2024).
breast cancer (continued). "Since RB1 loss-of-function alterations confer resistance to CDK4/6i in ER+ metastatic breast cancer patients, a genome-wide CRISPR screen identified protein arginine methyltransferase 5 (PRMT5) as a vulnerability in ER+/RB1-deficient breast cancer cells." (PMID 38672640, 2024). "CDK4/6 inhibitors have improved the PFS in patients with metastatic ER+/HER2- breast cancer." (PMID 38344632, 2024). "CDK4/6 inhibitors are the first-line treatment for HR+/HER2- advanced breast cancer." (PMID 39114308, 2024). "Blood creatinine increased had been observed in patients with breast cancer treated with CDK4/6 inhibitors, and cystatin C may be added for renal function assessment to facilitate subsequent treatment formulation." (PMID 39640578, 2024). "As CDK4/6 inhibitor (CDK4/6i) approval changed treatment strategies for patients with hormone receptor-positive HER2-negative (HR+/HER2-) breast cancer (BC), understanding how exposure to CDK4/6i affects the tumor genomic landscape is critical for precision oncology." (PMID 38388477, 2024). "Therefore, superior to pRb, the status of CDK4 phosphorylation was able to predict the response to palbociclib in 27/28 mesothelial cell lines, as we also observed it in breast cancer." (PMID 36453028, 2024). "Remarkably, mouse experiments unambiguously revealed that the medium dose of neratinib not only retained its potential to enhance the efficacy of CDK4/6 inhibitor combined with endocrine therapy in HR+/HER2-low breast cancer but also had good tolerability (P < 0.001)." (PMID 39730704, 2024). "The outcomes clearly demonstrated that the triple combination exerted significantly enhanced inhibitory effects on proliferation and colony formation in HR+/HER2-low breast cancer cells, surpassing the efficacy of CDK4/6 inhibitor combined with endocrine therapy alone (CI < 0.5, P < 0.01)." (PMID 39730704, 2024). "Thus, we present a retrospective analysis of breast cancer patients treated at our institution with the CDK4/6i combined with SABR." (PMID 39120877, 2024). "Furthermore, we demonstrated that pharmacological MAP3K3 inhibition can overcome YAP-induced resistance to CDK4/6 inhibitors in breast cancer cells and to BRAF inhibitors in melanoma cells, underscoring the therapeutic relevance of our findings." (PMID 38622197, 2024). "The use of CDK4/6 inhibitors in combination with aromatase inhibitors or fulvestrant has fundamentally changed the treatment of ET resistance in hormone receptor-positive (HR+)/HER2-negative (HER2−) breast cancer." (PMID 39338149, 2024). "All of the patients with LA-HR+/HER2- breast cancer would have likely benefited from extended endocrine therapy as well as adjuvant cyclin-dependent kinase 4/6 inhibitors, though it is likely that many of the patients did not receive these treatments in the given study period." (PMID 39594785, 2024). "Endocrine therapy, usually with an aromatase inhibitor in post-menopausal females, combined with a CDK4/6 inhibitor is the first-line treatment for advanced breast cancer positive for estrogen and/or progesterone (ER+/PR+) hormone receptor and HER2- overexpression." (PMID 39099917, 2024). "Robust YAP activation was observed in CDK4/6 inhibitor-resistant luminal breast cancer cells." (PMID 38622197, 2024). "Notably, CDK4/6 inhibitors have demonstrated remarkable efficacy in specific cancer types, particularly in estrogen receptor-positive (ER+) breast cancer." (PMID 39254653, 2024). "Thus, we performed a retrospective study to assess the role of locoregional RT in patients diagnosed with advanced breast cancer who undergo CDK4/6 inhibitor treatment in a first-line setting." (PMID 39065777, 2024). "Several non-clinical and clinical studies support the combination of PAM inhibitors and CDK4/6 inhibitors in tumors other than breast cancer, based on the rationale that these two pathways can compensate for each other when these inhibitors are used as single agents." (PMID 39456616, 2024).
breast cancer (continued). "CDK4/6i have revolutionised the landscape of breast cancer at both metastatic and early stages." (PMID 39090361, 2024). "In addition, a study confirmed that acute kidney injury in six biopsies-confirmed patients with HR+/HER2-breast cancer was directly related to CDK4/6 inhibitors." (PMID 39640578, 2024). "VERITAC-2 (ClinicalTrials.gov identifier: NCT05654623) is a phase 3 study that compares the efficacy and safety of vepdegestrant with fulvestrant in patients with ER+/HER2− advanced breast cancer after prior combination endocrine therapy and CDK4/6 inhibitor therapy." (PMID 39767607, 2024). "The present study aimed to evaluate the suppressive effect of CDK4/6 inhibitor in combination with endocrine therapy in HR+/HER2-low breast cancer and to explore the specific mechanism by which neratinib improves the efficacy of CDK4/6 inhibitor in combination with endocrine therapy." (PMID 39730704, 2024). "Four FDA-approved antagonists specifically target CDK4/6 for the treatment of breast cancer." (PMID 39404419, 2024). "Both domestic and foreign guidelines to treat hormone receptor-positive breast cancer recommend a CDK4/6 inhibitor combined with endocrine therapy as the preferred initial treatment for patients with luminal-type breast cancer following the development of endocrine therapy." (PMID 39544302, 2024). "CDK4/6i are a cornerstone of the management of ER + /HER2− breast cancers." (PMID 39090361, 2024). "CDK4/6 inhibitors are effective as a treatment for breast cancer." (PMID 38756650, 2024). "The direct inhibition of CDK4 by ellagic acid suppressed breast cancer proliferation." (PMID 38476024, 2024). "A systematic search was conducted across PubMed, Web of Science, Cochrane Library, and GeenMedical databases to identify randomized controlled trials investigating the use of CDK4/6 inhibitors in combination with endocrine therapy for the treatment of HR+/HER2-breast cancer." (PMID 38832268, 2024). "In advanced breast cancer patients treated with CDK4/6i, SABR provides a high local control and may provide additional benefit in an oligometastatic setting." (PMID 39120877, 2024). "Numerous randomized controlled trials (RCTs) have conclusively demonstrated that the combination of CDK4/6 inhibitors with ET effectively manages HR+/HER2-breast cancer, curtails the dissemination of cancer cells, and markedly improves patients' quality of life and survival rates." (PMID 38832268, 2024). "BM are common in breast cancer, and CDK4/6i show promise in patients with bone-only metastases." (PMID 38409585, 2024). "Analysis of tumor sizes in mice with the HR+/HER2-low breast cancer subtype revealed marked differences among the control (normal saline), CDK4/6 inhibitor + endocrine therapy, and triple combination (neratinib + CDK4/6 inhibitor + endocrine therapy groups (P < 0.05, P < 0.01)." (PMID 39730704, 2024). "Furthermore, all three classic CDK4/6i exhibited comparable efficacy and had the potential to mitigate disease progression in breast cancer patients with BM." (PMID 38409585, 2024). "These encouraging results prompted the phase III CAPItello-291 trial, which looked into the safety and effectiveness of this joint therapy for patients with AI-resistant advanced HR+/HER2− breast cancer, particularly those who had undergone CDK4/6 inhibitors treatment before." (PMID 38339303, 2024). "Moreover, in breast cancer, the loss of CDKN1A expression greatly reduces the sensitivity of cell cycle-related drugs such as CDK4/6 inhibitors and paclitaxel." (PMID 39268503, 2024). "In ER+ breast cancer cell lines that have become oestrogen independent following long term oestrogen deprivation, or resistant to the CDK4/6 inhibitor palbociclib increases in pS6 and other markers downstream of AKT are observed but little pAKT is detected or minimal to no change in pAKT." (PMID 38396173, 2024).